NMBR (neuromedin B receptor)
Description:
Receptor for neuromedin-B. Contributes to the maintenance of basal sigh rate through signaling in the pre-Botzinger complex, a cluster of several thousand neurons in the ventrolateral medulla responsible for inspiration during respiratory activity (By similarity). Contributes to the induction of sneezing following exposure to chemical irritants or allergens which causes release of NMB by nasal sensory neurons and activation of NMBR-expressing neurons in the sneeze-evoking region of the brainstem (By similarity). These in turn activate neurons of the caudal ventral respiratory group, giving rise to the sneezing response (By similarity). Contributes to induction of acute itch, possibly through its activation on dorsal root ganglion neurons by the NMB peptide (By similarity). Plays a role in the innate immune response to influenza A virus infection by enhancing interferon alpha expression and reducing expression of IL6. Plays a role in CSF1-induced proliferation of osteoclast precursors by contributing to the positive regulation of the expression of the CSF1 receptor CSF1R (By similarity).
Synonyms: NMB-R; BB1; BB1R; BRS1
Tractability: Small molecule: a high-quality ligand is known; it belongs to a druggable protein family. Antibody: UniProt places it where antibodies can reach, with high confidence; its Gene Ontology location is reachable by antibodies, with high confidence; UniProt predicts a signal peptide or a membrane-spanning region; the Human Protein Atlas places it where antibodies can reach. PROTAC: a small molecule that binds it is known.
Target class: Membrane receptor; Peptide receptor (family A GPCR); Short peptide receptor (family A GPCR); Family A G protein-coupled receptor; Neuromedin receptor
Gene: Protein-coding gene on chromosome 6 (142,058,330 to 142,147,122, reverse strand). Ensembl gene ENSG00000135577.
Subcellular location: Cell membrane
Subcellular location (Human Protein Atlas): Cytosol; Plasma membrane
Pathways (Reactome):
Signal Transduction: G alpha (q) signalling events; Peptide ligand-binding receptors
Gene Ontology:
Molecular function: bombesin receptor activity; neuropeptide receptor activity; G protein-coupled peptide receptor activity; G protein-coupled receptor activity
Biological process: antiviral innate immune response; negative regulation of interleukin-6 production; positive regulation of interferon-alpha production; G protein-coupled receptor signaling pathway; phospholipase C-activating G protein-coupled receptor signaling pathway; positive regulation of osteoclast proliferation; positive regulation of respiratory gaseous exchange; sneeze reflex; bombesin receptor signaling pathway; neuropeptide signaling pathway
Cellular component: cytosol; plasma membrane; membrane
Genetic constraint (gnomAD): Loss-of-function variants: 14 observed, 20.27 expected, observed/expected ratio (o/e) 0.69, 90% interval 0.46 to 1.08. The upper end of that interval is the gene's LOEUF score, 1.08, which puts it in group 4 of 6, group 1 being the genes least tolerant of losing a copy. Missense variants: 572 observed, 520.21 expected, observed/expected ratio (o/e) 1.1, 90% interval 1.03 to 1.18. Synonymous variants: 211 observed, 208.69 expected, observed/expected ratio (o/e) 1.01, 90% interval 0.9 to 1.13.
Homologues: Orthologues: chimpanzee NMBR (98% identical), macaque NMBR (96% identical), mouse Nmbr (91% identical), pig NMBR (90% identical), dog NMBR (90% identical), rabbit NMBR (89% identical), rat Nmbr (89% identical), guinea pig NMBR (87% identical), tropical clawed frog nmbr (75% identical), zebrafish nmbr (65% identical), Drosophila melanogaster CCHa1-R (34% identical), Drosophila melanogaster CCHa2-R (33% identical). Paralogues in human: GRPR (55% identical), BRS3 (46% identical), EDNRB (29% identical), EDNRA (25% identical), GPR37 (24% identical), NMUR1 (21% identical), NTSR1 (21% identical), NMUR2 (20% identical), MLNR (19% identical), GPR37L1 (19% identical), GHSR (19% identical), TRHR (19% identical), and 3 more.
Diseases named in the same sentence as NMBR in open-access papers:
NMBR is named in the same sentence as 34 diseases in open-access papers, as found by Europe PMC text mining. Sharing a sentence is not in itself a finding about the gene and the disease. The quoted sentences say what the papers report.
breast carcinoma (4 papers, 2013 to 2025). "In the present study, we found that exposure to hypoxic conditions increases the levels of NMBR mRNA and protein in breast cancer cells, which are tightly regulated by hypoxia-inducible factor-1α (HIF-1α)." (PMID 24349381, 2013). "For example, the neuromedin B receptor (NMBR), a bombesin receptor subtype closely related to GRPR, was found to be transcriptionally upregulated under hypoxic conditions via HIF-1α in breast cancer cells." (PMID 41226822, 2025). "Here, we provide the first insights regarding the molecular mechanisms of NMBR regulation in breast cancer cells by demonstrating that hypoxia increased NMB-R expression in human cancer cells and that HIF-1α directly bound to and transactivated the NMBR promoter in response to hypoxia." (PMID 24349381, 2013).
glioma (4 papers, 2013 to 2024). A benign or malignant brain and spinal cord tumor that arises from glial cells (astrocytes, oligodendrocytes, ependymal cells). "NMBR encodes a Neuromedin B receptor, and its mutations were previously reported in gliomas." (PMID 23301059, 2013). "In another study the NMBR in C-6 rat glioma cells was further characterized and compared to the human NMBR." (PMID 34539578, 2021). "Other studies demonstrated that the NMBR on rat glioma C-6 cells underwent desensitization, downregulation with internalization, and desensitization in a similar manner to human NMBRs transfected in normal cells." (PMID 34539578, 2021). "One study investigated the mRNA expression levels of each of the human BnRs (GRPR, NMBR, BRS-3) in recurrent gliomas in nine patients." (PMID 34539578, 2021). "However, in another study, the proliferation of the rat glioma C-6 cell line was stimulated by Bn (which can activate both GRPR and NMBR), and this effect was inhibited by the GRPR antagonist RC-3095." (PMID 34539578, 2021). "All gliomas had uptake and correlated with tumor density of GRPR, not NMBR/BRS-3." (PMID 34539578, 2021).
itch (2 papers, 2013 to 2017). "Together, the present study not only improves the understanding of itch neurotransmission in the spinal cord but also lays out the pharmacological basis for the development of GRPr and NMBr antagonists for the treatment of pruritus." (PMID 23826298, 2013).
prostate carcinoma (2 papers, 2012 to 2019). A carcinoma that arises from epithelial cells of the prostate gland. "However, BBS acts on two other receptors, neuromedin B receptor (NMB-R) and BBS receptor subtype 3 (BRS-3), shown to be expressed in 14% and 9% of prostate carcinomas respectively." (PMID 22715899, 2012).
adenoma (1 paper, 2013). A neoplasm arising from the epithelium. "Third, we found OR6X1 and NMBR, which are involved in olfactory transduction and neuroactive ligand-receptor interaction, respectively, are mutated in the adenoma." (PMID 23301059, 2013).
anxiety disorder (1 paper, 2024). A category of psychiatric disorders which are characterized by anxious feelings or fear often accompanied by physical symptoms associated with anxiety. "Notably, among the four DE GPCRs identified in both models, Smo has established associations with depressive or anxiety disorders, and our previous study has revealed the role of neuromedin B (NMB) receptor (NmbR) in developing depressive-like symptoms in the animal model." (PMID 38670310, 2024).
Arthritis (1 paper, 2025). Inflammation of a joint. "The activation of NMBR can influence proinflammatory cytokine release in arthritis or asthma models, potentially by inducing IL-17 expression." (PMID 41455906, 2025).
atopic dermatitis (1 paper, 2013). "Nevertheless, it is worth evaluating GRPr and NMBr antagonists in animal models of chronic itch such as atopic dermatitis and cholestasis." (PMID 23826298, 2013).
breast tumor (1 paper, 2013). "NMBR is aberrantly expressed by various types of solid tumors such as lung, prostate, colorectal, and breast tumors." (PMID 24349381, 2013).
cervical cancer (1 paper, 2024). A primary or metastatic malignant neoplasm involving the cervix. "When the binding between NMB and NMBR was blocked, the damaged limb function three days post cervical cancer inoculation was reduced, showed by the alleviated sciatic nerve index and sciatic nerve score." (PMID 39214988, 2024). "The NMBR-specific antagonist PD168368 was then used to confirm the NMBR-initiated PNI of cervical cancer." (PMID 39214988, 2024). "The effect of NMB on axon regeneration was analyzed in the DRG-cervical cancer co-culture model, and the regenerated neurites were significantly decreased by the deficiency of NMB or the inhibition of NMBR." (PMID 39214988, 2024). "Moreover, NMBR antagonist reduced the damage of nerves by the inoculation of cervical cancer cells, showed by HE and PGP9.5 staining." (PMID 39214988, 2024). "Moreover, NMBR antagonist inhibited the PNI of cervical cancer in the ME180 subcutaneous tumor-bearing model." (PMID 39214988, 2024). "Mechanistically, cervical cancer cells-produced NMB activated its receptor NMBR in Schwann cells, and opened the T-type calcium channels to stimulate Ca2+ influx through PKA signaling, which could be blocked by the inhibitor." (PMID 39214988, 2024).
endometriosis (1 paper, 2025). The growth of functional endometrial tissue in anatomic sites outside the uterine body. "In the merged dataset, the expression levels of these six genes—DDR2, ENO3, ESM1, NMBR, PRKAB1, and PRPF19—showed significant differences between normal and endometriosis samples (DDR2, p < 0.001; ENO3, p < 0.001; ESM1, p < 0.001; NMBR, p = 0.002; PRKAB1, p < 0.001; PRPF19, p < 0.001)." (PMID 41424583, 2025).
Insulin resistance (1 paper, 2019). Increased resistance towards insulin, that is, diminished effectiveness of insulin in reducing blood glucose levels. "In summary, consumption of NNS may activate GPCR signaling pathways that lead to cross-activation of insulin receptors through the neuromedin B receptor (NMBR) and ultimately promote the development of insulin resistance and T2DM." (PMID 30884834, 2019).
medulloblastoma (1 paper, 2021). A malignant, invasive embryonal neoplasm arising from the cerebellum. "No studies have examined the signaling cascades of BnRs (GRPR, NMBR) in medulloblastomas." (PMID 34539578, 2021). "A later study of the medulloblastoma cell lines DAOY and D283 reported both cell lines expressed NMBR mRNA and NMB mRNA." (PMID 34539578, 2021). "In contrast to the growth inhibitory effect of higher concentrations of cetuximab in the medulloblastoma cell line DAOY, neither the addition of NMB nor the NMBR antagonist BIM-23127 had an effect on the cell line’s growth or viability when present alone." (PMID 34539578, 2021).
virus infection (1 paper, 2019). "The expression level of NMB was slightly increased, whereas the expression of NMBR was clearly increased, in 293T cells in response to virus infection." (PMID 31601264, 2019). "However, the expression profiles of NMB and NMBR during IAV infection and the activity of NMB/NMBR in hosts during virus infection remain unclear." (PMID 31601264, 2019).
cancer (7 papers, 2013 to 2025). A tumor composed of atypical neoplastic, often pleomorphic cells that invade other tissues. "Upregulated GPCRs that have been proposed as therapeutic targets in cancer included the adenosine receptors ADORA1 and ADORA3, and important GPCRs for autocrine growth factors in cancer, such as bombesin receptor NMBR, and neurotensin receptor NTSR145,46." (PMID 36220861, 2022). "The bombesin (Bn) receptor family [Gastrin-releasing peptide (GRPR/BB2R) and Neuromedin B receptors (NMBR/BB1R)] are G-protein coupled receptors (GPCR’s) with potent growth effects on normal tissues/numerous cancers, often by transactivating the ErbB receptor-tyrosine kinase (RTK) family." (PMID 41007372, 2025). "Considering the differences of enzyme activity of PHDs and tissue distribution of PHDs may result in a graded or cell- or tissue-specific response to hypoxia, it would be of interest to explore the expression of cancer type-specific NMBR and its regulation in human cancers." (PMID 24349381, 2013). "However, the mechanism that regulates NMBR expression in cancer cells exposed to environmental stimuli is unknown." (PMID 24349381, 2013). "This family of peptide receptors contains gastrin-releasing peptide receptor (GRPR), neuromedin B receptor (NMBR), and bombesin receptor subtype 3 (BRS3), which are overexpressed by a number of cancers, including PDAC." (PMID 29865257, 2018).
tumor (5 papers, 2000 to 2024). "However, a G protein-coupled receptor encoding gene, NMBR, is known to play a critical role in tumor development, invasion, and metastasis." (PMID 30305115, 2018). "NMB secreted from tumor cells induced Schwann cell activation and axonal extension, which could be blocked by the selective NMBR antagonist PD168368." (PMID 39214988, 2024). "The co-localization of NMBR and GFAP were observed in tumor-invading sites of sciatic nerve, with a Pearson’s colocalization coefficient of 0.41 and 0.81 in Hela and ME180 PNI models, presenting that NMBR is located in activated Schwann cells." (PMID 39214988, 2024).
infection (3 papers, 2017 to 2025). The state of being infected such as from the introduction of a foreign agent such as serum, vaccine, antigenic substance or organism. "This conclusion was supported by the fact that the depletion of NMBR increased the susceptibility of host cells to PR8 infection." (PMID 31601264, 2019). "Similar profiles of both NMB and NMBR expression following infection with PR8 were also observed in A549 cells." (PMID 31601264, 2019). "Although it appears from the data presented here that induction of NMBR in response to IAV/PR8 infection is indeed part of the host innate response and is detrimental to the virus, further studies are necessary to confirm these findings." (PMID 31601264, 2019). "Similarly to above, it was observed that the expression of NMB and NMBR increased in lung tissues following infection with PR8." (PMID 31601264, 2019). "Furthermore, the NMB/NMBR system appeared to increase IFN-α expression and decrease IL-6 expression after PR8 infection, which may serve to establish an antiviral state in the host." (PMID 31601264, 2019).
NMBR also shares sentences with these, for which no sentence is quoted: lung carcinoma (3 papers); colorectal adenoma (2); Alzheimer disease (1); Arrhythmia (1); asthma (1); Brugada syndrome (1); cardiac arrhythmia (1); cardiovascular disease (1); cholestasis (1); colorectal cancer (1); dilated cardiomyopathy (1); glioblastoma (1); long QT syndrome (1); malignant glioma (1); neuroblastoma (1); non-small cell lung carcinoma (1); sick sinus syndrome (1).